TSPO (translocator protein)
Diseases named in the same sentence as TSPO in open-access papers (continued):
Sharing a sentence is not in itself a finding about the gene and the disease.
Stroke (continued). "Such combination of techniques allowed the authors to determine that brain regions with early phagocytic signal (USPIO+) at day 7 will irremediably evolve into necrotic tissue, whereas tissue exclusively positive for TSPO will remodel but remains viable thereafter (days 27 and 55 post-stroke)." (PMID 34245328, 2021). "Moreover, studies of cortical strokes have used a variety of multilabel immunofluorescence combinations to investigate the cellular origin of TSPO in stroke." (PMID 32990808, 2020). "A TSPO molecular imaging biomarker 11C-vinpocetine showed different time-dependent decreases between microglial activation in the peri-infarct zone and the ischaemic core of stroke." (PMID 32252470, 2020). "In imaging studies, TSPO is hardly detectable in a healthy brain, whereas it becomes highly upregulated under pathological conditions, such as multiple sclerosis or stroke and in chronic neurodegenerative diseases, such as Alzheimer’s, ALS, or some lysosomal storage disorders." (PMID 33113845, 2020). "Remote WM TSPO cell counts were low and unaffected by stroke." (PMID 32990808, 2020). "Further, as mentioned, non-TSPO targeting agents may also reduce the inflammatory response after stroke." (PMID 32252470, 2020). "The novel TSPO tracer 18F-GE-180 was also tested in a rat model of stroke." (PMID 32252470, 2020). "Interestingly, TSPO expression as well as binding of its ligands are upregulated in stroke and neurodegenerative disorders, implicating a regulatory role of mitochondrial TSPO in neurosteroid-mediated neuroprotection in pathological states." (PMID 30853890, 2019). "Additionally, preblocking with cold PK11195 revealed significantly decreased binding of both tracers in dMCAO mice at 6 d after stroke, confirming the specificity of both tracers for TSPO." (PMID 29976695, 2019). "While such effects may be present in some patient groups, such as patients with stroke, caution is advised for disorders for which increases in TSPO might be more subtle." (PMID 30498919, 2018). "TSPO expression in milder stroke patients is thus unavailable." (PMID 30034558, 2018). "TSPO has been used as a biomarker of brain injury and inflammation in various neurological diseases, including dementia, degenerative diseases, multiple sclerosis, encephalitis, and stroke." (PMID 30034558, 2018). "However, if TSPO imaging in acute conditions such as stroke provides strong and reliable signals, TSPO imaging in neurodegenerative diseases has proven more challenging." (PMID 27481358, 2017). "Furthermore, Thiel and Heiss found an increase of TSPO expression in the CNS up to 4 weeks after human stroke." (PMID 23936336, 2013). "The dynamic changes in PET scans with radiotracers of TSPO, which are putative markers of microglia activation and neuroinflammation in stress-related brain inflammation, can indicate a fluctuation in the inflammatory response following stroke over a period of 90 days." (PMID 39224610, 2024). "Moreover, previous studies revealed that the degree of microglial activation appeared to be directly correlated with the degree of white matter fibre damage on MRI, which persisted in longitudinal TSPO PET assessments for up to six months after the index stroke." (PMID 37193998, 2023). "Thus, we hypothesise that the dynamic range of changes on TSPO expression induced by a HT diet might be hidden by the stroke effect and PET sensitivity." (PMID 33754046, 2021). "Thus, TSPO based treatments of brain disease and brain injury, including stroke, may become increasingly more successful." (PMID 32252470, 2020). "Both PK and newer TSPO ligands have been key in elucidating how changes in TSPO expression, both spatially and temporally, relate to the pathogenesis of stroke and highlight a conceivable role for novel anti-inflammatory substances in the long-term management of stroke." (PMID 31139952, 2019).
Stroke (continued). "However, the initial TSPO level was not correlated with the baseline stroke severity, suggesting that TSPO is not directly linked to the stroke location or the infarct size." (PMID 30034558, 2018). "The aim of this study was to measure the level of TSPO in a small number of patients with acute ischemic stroke and to determine whether plasma TSPO levels reflect the degree of stroke severity and can predict stroke outcomes." (PMID 30034558, 2018). "Prior studies have reported that the expression of translocator protein (TSPO) was enhanced in activated microglia, and [18F]‐DPA‐714 exhibited highly specific binding to TPSO ligands post‐stroke." (PMID 38421089, 2024). "To assess stroke-induced neuroinflammation, we performed serial PET imaging with 18F-GE180 and evaluated TSPO upregulation in the MRI-defined stroke territory." (PMID 36279013, 2022). "In a rat model of photothrombotic stroke at 24 h after surgery, increased [11C]NE40 (CB2R tracer) uptake and unvaried [11C]PK11195 (TSPO tracer) uptake were reported." (PMID 34642898, 2022). "In a rat stroke model, [18F]DPA-714 (TSPO) signal within the infarcted area peaked around day 10-14 post ischemia, a signal mostly induced by microglia/macrophages 64 while a greater astrocytic contribution to the signal was observed at latter time points." (PMID 33754046, 2021). "In that perspective, some studies used TSPO-PET imaging to better characterize the temporal and anatomical evolution of neuroinflammation in various models of experimental stroke, some of them new." (PMID 34245328, 2021). "Future work will focus on investigating the relationship between TSPO PET signal, neurologic symptoms, and long-term outcomes in rodent models and stroke patients." (PMID 29976695, 2019). "Results from this study highlight the utility of TSPO PET as an invaluable tool for deciphering the in vivo role of neuroinflammation in both early and late stages after stroke in the central nervous system and periphery." (PMID 29976695, 2019). "Currently, an ongoing clinical trial since 2020 (NCT04412187) employs TSPO-PET imaging technology to dynamically monitor the phenotypic switching of microglia and systematically assess the evolution of neuroinflammation post-stroke." (PMID 41280893, 2025). "The purpose of our pilot study was to describe the spatio-temporal profile of brain inflammation after stroke using 18kD translocator protein (TSPO) positron emission tomography (PET) with magnetic resonance (MR) co-registration in the subacute and chronic stage after stroke." (PMID 37193998, 2023). "Considering EVs released by endothelial cells in stroke patients, TSPO was diminished both on CD106+ and CD31+ EVs, without statistical significance compared to controls (Mann–Whitney test)." (PMID 37175644, 2023). "However, regression analysis revealed that mice with lower TSPO signal at 7 days after injury tended to exhibit higher ejection fraction at 3 weeks, suggesting that more effective microglial suppression during stroke progression may partly spare cardiac function." (PMID 36279013, 2022). "Because of the improved bioavailability, specificity, and signal-to-noise ratio of 18F-DPA-714 compared with other TSPO tracers, 18F-DPA-714 was used in target validation studies on preclinical and clinical stroke and to track the response to immunomodulatory treatment." (PMID 34168016, 2022). "Overall, we can conclude that TSPO-PET imaging is a powerful tool to evaluate the neuroinflammatory response in models with strong and localized effects, such as intracerebral administered toxic lesion models (LPS, QA, 6-OHDA) and stroke models." (PMID 34245328, 2021). "On top of characterizing the temporal evolution of TSPO expression after stroke, some studies used TSPO-PET tracers combined with other PET tracers or other imaging methods to investigate further processes in stroke." (PMID 34245328, 2021).
Stroke (continued). "In addition, the role of A1ARs on stroke inflammation using pharmacological modulation was assessed with magnetic resonance imaging (MRI), PET imaging with [18F]DPA-714 (TSPO) and [18F]FLT (cellular proliferation), as well as IHC and neurofunctional studies." (PMID 33391483, 2021). "TSPO radiotracers, other than 11C-PK11195 for PET analysis, have been applied to stroke research." (PMID 32252470, 2020). "TSPO PET imaging has to date been used mainly to assess microglial activation in various neurologic diseases ranging from neurodegenerative disorders such as Huntington's disease and Alzheimer's disease to stroke and psychiatric conditions like schizophrenia." (PMID 29114179, 2017). "Similarly, focusing on microglia-derived EVs, TSPO was found more abundant on CD11b+ EVs in stroke patients than CTRL, but not on IB4+ EVs." (PMID 37175644, 2023). "Indeed, in neuron-derived EVs of stroke patients, TSPO was found to increase in CD171+ EVs, but not in the Ephrin B+ vesicles." (PMID 37175644, 2023). "Total body TSPO PET enables monitoring of neuroinflammation, providing insights into brain–heart inter-organ communication and may guide therapeutic intervention to spare cardiac function post-stroke." (PMID 36279013, 2022). "Nonetheless, the TSPO signal in the heart correlated with the severity of contractile impairment, suggesting a mechanistic contribution of mitochondrial dysfunction to stroke-induced cardiac damage, independent of systemic inflammation and immune cell mobilization." (PMID 36279013, 2022). "The observed differences in increased uptake exceeding MRI correlates of ischemia in PACNS in contrast to uptake restricted to MR-abnormalities in stroke of non-inflammatory origin allow to raise the hypothesis of specific cerebral TSPO distribution in PACNS." (PMID 31960097, 2020). "However, few head-to-head studies have been conducted to date, and none have compared 2 second-generation TSPO tracers in stroke models." (PMID 29976695, 2019). "Further, despite excluding patients with active infection at stroke onset, other factors that might contribute to elevated TSPO were not elucidated." (PMID 30034558, 2018). "Although an increase in uptake of TSPO tracers in the infarct has been well documented along with the cellular source of TSPO using other microglial markers such as Cd11b and Iba1, to our knowledge, rodent studies have only investigated cortical strokes as opposed to subcortical strokes." (PMID 32990808, 2020). "Overall, GFAP and iNOS concurred with TSPO immunohistochemistry, with no significant changes in remote WM following ET1-induced stroke." (PMID 32990808, 2020). "TSPO and iNOS were not able to detect the chronic WM microglial activation that was detected with MHCII in the contralateral corpus callosum (day 28 OX6% area: saline = 0.62 ± 0.38; stroke = 4.30 ± 2.83; P = .029)." (PMID 32990808, 2020). "For these reasons, TSPO PET may not provide unequivocal, longitudinal measurements for guiding subject-specific infarct-targeted anti-inflammatory therapy after stroke in rodent models." (PMID 32990808, 2020).
glioblastoma (45 papers, 2014 to 2025). The most malignant astrocytic tumor (WHO grade IV). "A study investigated the role of TSPO genetic variant, namely the rs6971 polymorphic variant, and its correlation with the outcome of glioblastoma patients." (PMID 38585455, 2024). "On the one hand, TSPO is known to be directly involved in glioblastoma hallmark features such as proliferation, migration and invasion." (PMID 38255293, 2024). "Remote neuroinflammation in patients with glioblastoma was associated with higher TSPO expression of the tumor and larger tumor extent, also showing regional dependency from the primary tumor site." (PMID 39150564, 2024). "Additionally, the association between TSPO genetic polymorphism A147T and poorer outcomes in male glioblastoma patients parallels our findings on TSPO's prognostic value." (PMID 40550494, 2025). "ROS was significantly reduced in TSPO-deficient glioblastoma." (PMID 36278207, 2022). "Furthermore, activation of TSPO by NO is associated with apoptosis in glioblastoma cell lines via collapse of mitochondrial membrane potential, mitochondrial ROS formation and DNA fragmentation, revealing a link between TSPO-NO cytotoxicity." (PMID 27544883, 2016). "Molecularly, high TSPO expression seems to mark prognostically unfavorable glioblastoma cell subpopulations characterized by an enrichment of mesenchymal gene sets and higher amounts of tumor-associated macrophages." (PMID 41019666, 2025). "Although increasingly explored in glioblastoma, findings related to TSPO are complicated by the coincidence of its expression in both TAMs and tumor cells." (PMID 38255293, 2024). "Back-translation into a glioblastoma mouse model reflected the increase of contralateral TSPO expression and identified myeloid cells as the source of elevated TSPO-PET signals in distant brain tissue." (PMID 39150564, 2024). "Our study revealed elevated TSPO-PET signals in contralateral hemispheres of patients with newly diagnosed glioblastoma compared to healthy controls." (PMID 39150564, 2024). "From a translational perspective, our findings indicate that TSPO-PET facilitates in vivo assessment of an altered immune cell signature not only in the tumor but also throughout the whole brain of patients with glioblastoma." (PMID 39150564, 2024). "In summary, our data show an association of the disease course not only with the local tumor site but also with distant TSPO expression in patients with newly diagnosed glioblastoma." (PMID 39150564, 2024). "We identify the invasive inoculation process used for generating orthotopic glioblastoma in vivo models to be a relevant contributor to the TSPO radioligand uptake in the GL261 glioblastoma mouse model." (PMID 38255293, 2024). "TSPO tracer uptake of the contralateral hemisphere of glioblastoma mice was driven by CD11b positive myeloid cells with only minor impact of other cell types." (PMID 39150564, 2024). "In summary, our back-translation approach clearly identified elevated TSPO expression and tracer uptake of myeloid cells as the cellular correlate of high contralateral TSPO-PET signals in glioblastoma." (PMID 39150564, 2024). "The coexistence and assumed crosstalk of these diverging roles of TSPO in glioblastoma are currently of high interest in order to better understand and enhance the interpretability of TSPO PET imaging results in glioblastoma." (PMID 38255293, 2024). "In particular, TSPO-PET imaging revealed higher contralateral signals in patients with newly diagnosed glioblastoma compared to patients with newly diagnosed IDHmut astrocytoma WHO 2 and healthy controls." (PMID 39150564, 2024). "To pinpoint underlying sources of contralateral TSPO-PET signal elevations in depth, we back-translated the PET analysis into an SB28 glioblastoma mouse model." (PMID 39150564, 2024). "SB28 glioblastoma mice indicated higher TSPO-PET signals compared to contralateral hemispheres of sham mice (SUVr: +18%, P = 0.032; VTr: +16%, P = 0.0086)." (PMID 39150564, 2024).
glioblastoma (continued). "This analysis revealed that patients with glioblastoma showed higher TSPO-PET signals (P < 0.05, FDR corrected) in 60 out of 123 brain regions of the contralateral hemisphere compared to healthy controls, pronounced in the mesio-temporal lobe (+14%)." (PMID 39150564, 2024). "To minimize the impact of tumor infiltration, we focused on the contralateral hemisphere and compared TSPO-PET signals between patients with glioblastoma and healthy controls." (PMID 39150564, 2024). "Neuroinflammation within the contralateral hemisphere can be detected with TSPO-PET imaging and associates with poor outcome in patients with newly diagnosed glioblastoma." (PMID 39150564, 2024). "TSPO has been found up-regulated in several cancer cells including glioblastoma but its role in promoting tumor growth and proliferation is still not clear." (PMID 37238297, 2023). "In glioblastoma tissue samples of our TSPO-PET imaging study cohort, we dissected the association of TSPO tracer enrichment and protein labeling with the expression of cell lineage markers by immunohistochemistry and fluorescence multiplex stains." (PMID 37697350, 2023). "Molecularly, high TSPO expression marks prognostically unfavorable glioblastoma cell subpopulations characterized by an enrichment of mesenchymal gene sets and higher amounts of tumor-associated macrophages." (PMID 37697350, 2023). "Our data also identified translocator protein TSPO, previously shown to also be overexpressed in glioblastoma and worthy of consideration in any future combination therapies." (PMID 37637064, 2023). "Applied to human tissue, a similar picture together in low and high grade Glioblastoma patients was found, and moreover, they observed significantly higher TSPO radiotracer uptake of single tumor cells in high grade patients compared to low grade." (PMID 36952073, 2023). "This difference in TSPO expression even occurs among glioblastoma and other homogeneous molecular groups and correlates with higher tumor aggressiveness." (PMID 36329288, 2023). "Several studies have shown that TSPO expression is elevated in cancer and correlate with poor survival in glioblastoma, breast cancer, prostate cancer, liver cancer, colorectal cancer, melanoma, and esophageal squamous cell carcinoma." (PMID 38162485, 2023). "For example, 18 kDa translocator protein (TSPO) is expressed in glioblastoma and several other neurodegenerative disorders." (PMID 36607830, 2023). "Applied in vivo to a glioblastoma model in mice, and ex vivo in human glioblastoma tissue, using a TSPO radiotracer, they surprisingly observed that TSPO uptake was more intense in tumor cells than in immune cells." (PMID 36952073, 2023). "A human pilot study in patients with glioblastoma using the [18F]GE-180 tracer indicated that TSPO signal was found in areas beyond contrast-enhanced MR regions, with significant tumor-to-background contrast." (PMID 35804911, 2022). "The aim of this study was to perform a complete mechanistic analysis of NOX4-mediated TSPO-induced ROS elevation in angiogenesis in glioblastoma." (PMID 36278207, 2022). "In this study, targeting the specific ligand XBD173 showed that the TSPO signaling pathway played a key role in reducing angiogenesis in glioblastoma, consistent with the main pathological features of neovascular age-related macular degeneration." (PMID 36278207, 2022). "TSPO is one of the hallmarks of glioblastoma and its imaging has the potential to improve patient care drastically." (PMID 36293329, 2022). "In glioblastoma patients, [18F]-GE-180 showed improved tumor-to-background ratios compared to the former generation TSPO-targeting radioligands." (PMID 35788730, 2022). "We conducted conditional deletion of the translocator protein (TSPO) targeting the protein with the synthetic ligand XBD173 in the glioblastoma mouse model." (PMID 36278207, 2022).